DNAL4 (dynein axonemal light chain 4)
Description:
Force generating protein of respiratory cilia. Produces force towards the minus ends of microtubules. Dynein has ATPase activity (By similarity).
Synonyms: dJ327J16; PIG27; MRMV3
Tractability: Antibody: its Gene Ontology location is reachable by antibodies, with high confidence. PROTAC: ubiquitination databases record sites on it; its protein half-life has been measured.
Gene: Protein-coding gene on chromosome 22 (38,778,508 to 38,794,198, reverse strand). Ensembl gene ENSG00000100246.
Subcellular location: Cytoplasm, cytoskeleton, cilium axoneme
Subcellular location (Human Protein Atlas): Acrosome; Basal body; Centrosome; Calyx; Cytosol; Equatorial segment; Nucleoli; Nucleoplasm; Perinuclear theca; Primary cilium transition zone; Principal piece
Pathways (Reactome):
Signal Transduction: Retrograde neurotrophin signalling
Gene Ontology:
Molecular function: identical protein binding; protein binding; microtubule motor activity
Biological process: microtubule-based movement; microtubule-based process
Cellular component: plasma membrane; axoneme; dynein complex
Genetic constraint (gnomAD): Loss-of-function variants: 10 observed, 11.72 expected, observed/expected ratio (o/e) 0.85, 90% interval 0.52 to 1.44. The upper end of that interval is the gene's LOEUF score, 1.44, which puts it in group 5 of 6, group 1 being the genes least tolerant of losing a copy. Missense variants: 128 observed, 126.12 expected, observed/expected ratio (o/e) 1.01, 90% interval 0.88 to 1.17. Synonymous variants: 46 observed, 47.81 expected, observed/expected ratio (o/e) 0.96, 90% interval 0.76 to 1.23.
Homologues: Orthologues: chimpanzee DNAL4 (100% identical), guinea pig DNAL4 (100% identical), macaque DNAL4 (100% identical), pig DNAL4 (100% identical), dog DNAL4 (99% identical), mouse Dnal4 (99% identical), rat Dnal4 (97% identical), rat Dnal4-ps1 (95% identical), zebrafish dnal4b (87% identical), tropical clawed frog dnal4 (86% identical), zebrafish dnal4a (86% identical), Drosophila melanogaster CG8407 (58% identical).
Diseases named in the same sentence as DNAL4 in open-access papers:
DNAL4 is named in the same sentence as 3 diseases in open-access papers, as found by Europe PMC text mining. Sharing a sentence is not in itself a finding about the gene and the disease. The quoted sentences say what the papers report.
Hypertension (1 paper, 2017). The presence of chronic increased pressure in the systemic arterial system. "Three detected genes were recognized by previous studies, and the other 5 loci/genes (MAN1A1, LMO3, NPAP1/SNRPN, DNAL4, and RNA5SP455/KRT8P5) were novel findings, which had no strong main effect on hypertension and could not be easily identified by single-locus genome-wide studies." (PMID 28642868, 2017).
infection (1 paper, 2022). The state of being infected such as from the introduction of a foreign agent such as serum, vaccine, antigenic substance or organism. "Thus, SIGLEC11 and DNAL4 appear to contribute to cell migration and infiltration to site of infection during TB." (PMID 36275677, 2022).
DNAL4 also shares sentences with these, for which no sentence is quoted: teratozoospermia (1 paper).